MUC1 (mucin 1, cell surface associated)
Diseases named in the same sentence as MUC1 in open-access papers (continued):
Sharing a sentence is not in itself a finding about the gene and the disease.
infection (continued). "To determine the importance of sialic acid residues on MUC1 for binding of EAEC, we pretreated MUC1-positive HEK293 cells with neuraminidase for 1 h prior to infection with the 042 wt strain." (PMID 28588132, 2017). "LewisX and MUC1 isolated from breast milk have been shown to inhibit binding of cell-free HIV-1 to DC-SIGN and to prevent transfer of infection to CD4+ T cells." (PMID 22952771, 2012). "Among the membrane bound and secreted mucins tested, MUC1, MUC20 and MUC6 transcription levels were observed to increase during the infection." (PMID 21569362, 2011). "Mice lacking the Muc1 and Muc5AC mucins have a higher H. pylori density after infection than wild-type mice." (PMID 40667878, 2025). "While the exact timing and degree to which MUC1 inhibits TLR pathways to reduce inflammatory responses remain unclear, this process is thought to be critical in controlling the severity of infection." (PMID 39469649, 2024). "As the lack of an increase in soluble MUC1 levels following infection of human airway cells was unexpected, we sought to further characterize MUC1 dynamics in HAE after IAV challenge." (PMID 35699372, 2022). "Together, these results indicate that expression of MUC1 on the cell surface does not form a physical barrier against infection but instead slightly enhances ITGB1-mediated uptake of E. coli inv." (PMID 33824202, 2021). "We performed similar experiments on the inhibition of Ha-CoV-2 infection by SHREKs, and found that in addition to PSGL-1, CD164, TIM-1, MUC1, and MUC4 also inhibited the infection of Ha-CoV-2 virus; The MUC4 vector had the strongest inhibition among these SHREKs." (PMID 34064525, 2021). "It was further shown that greater infection inhibition was achieved for the MUC1 peptide-blocked control when the MUC1 core peptide was in the infection media rather than premixed with the virus." (PMID 33869742, 2021). "Another limitation is that we assumed a fixed adaptive immune response, such that the adaptive immune responses dominate viral clearance at day 5 post infection regardless of MUC1 expression." (PMID 34066999, 2021). "Muc1 was found in Cluster020 where the average expression across all cluster genes of the Muc1−/− samples was half that of the wild type and there was no change during the infection in either WT or Muc1−/−." (PMID 32793510, 2020). "The results of GEO dataset (GSE74577) indicated that the expression of MUC1 but not TFF2 was significantly decreased in GES-1 cells after 24-h infection with H. pylori (P = 4.49 × 10− 4, P = 0.582, respectively)." (PMID 32122390, 2020). "In vitro infection studies with non-typeable Haemophilus influenzae also revealed that MUC1-CT inhibited the TLR2 signaling pathway." (PMID 31069176, 2019). "MUC1 not only binds to influenza virus and inhibits infection, but also in the absence of Muc1 expression, an enhanced inflammatory disease was experienced by the virus-infected mice." (PMID 29186029, 2017). "Other evidence of MUC1 as a negative controller of inflammation stems from studies of the inflammatory response to infection." (PMID 26751474, 2016). "Given that MUC1 from human milk and MUC6 from seminal plasma are known to inhibit DC-SIGN mediated HIV-1 trans-infection one might have expected another member of this family to be expressed in CM and binding DC-SIGN." (PMID 25793526, 2015).
infection (continued). "Our data indicate that the MUC expression by RSV and hMPV differs significantly, as we observed a stronger induction of MUC8, MUC15, MUC20, MUC21, and MUC22 by RSV infection while the expression of MUC1, MUC2, and MUC5B was dominated by the infection with hMPV." (PMID 25977598, 2015). "No major changes were observed in Muc1, Muc15 and Muc20 levels during chronic or acute infection when compared to uninfected control mice (day 21 pi." (PMID 21155842, 2011). "After 6 h of co-culture H. pylori strain J99 wt did not affect the level of MUC1 on the cell surface, however, it led to depletion of 44% of cell surface MUC1 after 24 h infection compared to uninfected MKN7 cells." (PMID 19816567, 2009). "Like the small intestine, Muc1 was not expressed in the caecum and there were no changes in mucin expression in response to infection." (PMID 19088856, 2008). "Therefore, our findings reveal that during infection of human respiratory Calu-3 cells the MUC1 extracellular domain rather than individual mucin glycans prevents the binding of SARS-CoV-2 to the underlying receptor." (PMID 37561789, 2023). "In the absence of Muc1, the kinetics of the infection are altered." (PMID 35774401, 2022). "Indeed, the significant difference in successful infection events after just 15 min of inoculation time suggests that a more rapid initial uptake of viral particles contributes to the enhanced replication and spread of IAV in MUC1-depleted cultures." (PMID 35699372, 2022). "IAV challenge in HAE lacking MUC1 reveals altered infection dynamics." (PMID 35699372, 2022). "We showed that the presence of MUC1 reduces AUCM, which may alleviate infection severity." (PMID 34066999, 2021). "Microscopy on the DOX+ MUC1-ΔCT cells incubated with E. coli inv showed that cells expressing the MUC1-ΔCT were rarely infected with E. coli, whereas the subset of cells that lacked expression of MUC1-ΔCT showed a high percentage of infection." (PMID 33824202, 2021). "To better understand the molecular mechanism by which MUC1 mediates the inhibition of gastric H. pylori colonization, we applied a microarray approach to examine the effect of Muc1 gene ablation on gastric gene expression in the absence of infection." (PMID 32793510, 2020). "Similarly to the mucus changes during different time points of infection in WT animals, Muc1, Muc2, Muc4 or Muc6 mRNA levels did not explain the differences in mucus thickness between IFN-γ−/- and WT mice." (PMID 30665337, 2019). "However, S100A1, MUC1, and TRIP6 showed a continued up-regulated status at 4 days post-infection." (PMID 21172007, 2010). "However, there were significant increases in the amount of shed MUC1 following knockdown of MMP-14 at 8 but not 24 h of infection, although no changes were seen following knockdown of ADAM17." (PMID 19816567, 2009). "However, MMP-14 only partially affected MUC1 shedding during infection and had no influence on MUC1 shedding in non-infected cells, indicating that other factors are involved in MUC1 release." (PMID 19816567, 2009). "Notably, no consensus on MUC1 function or dynamics during infection is reflected in these studies." (PMID 35699372, 2022). "Furthermore, they suggest that the absence of MUC1, while not driving a significant increase in cumulative viral load, facilitates viral replication and dissemination within the host in the early stages of infection." (PMID 34066999, 2021).
infection (continued). "Overexpression of TM mucins MUC1, MUC4 or MUC21 reduced infection by SARS-CoV-2 compared to cells with a non-targeting guide (NTG)." (PMID 37561789, 2023). "Increased gene expression of MUC1, MUC6 and MUC20 was observed, while MUC5AC did not change during infection." (PMID 21569362, 2011). "IAV upregulation of MUC1 protein in HAE was not exclusively dependent on IFN signaling, indicating that multiple soluble factors produced during infection may contribute to elevated MUC1 expression." (PMID 35699372, 2022). "The result demonstrated significantly positive correlation of MUC1 and TFF2 expression among GC patients with H. pylori infection but not for those without infection (total: r = 0.287, P = 0.028; H. pylori negative: r = 0.196, P = 0.318; H. pylori positive: r = 0.382, P = 0.034)." (PMID 32122390, 2020).
kidney disease (20 papers, 2017 to 2025). "For example, Mucin 1 kidney disease (MKD) is caused by a frameshift (fs) mutation in the MUC1 gene (MUC1-fs)." (PMID 39303030, 2024). "In conclusion, this study highlights the interplay between genetic predisposition and environmental factors potentially influencing the course of kidney disease by modulating the expression of harmful variants of MUC1." (PMID 37316299, 2023). "Genetic alterations comprising common low-effect to rare large-impact variants of kidney disease genes such as UMOD or MUC1 determine the susceptibility to the development of CKD." (PMID 37316299, 2023). "In this context, genetic alterations in the kidney disease gene MUC1 (Mucin1) predispose to the development of CKD." (PMID 37316299, 2023). "We identify a common alternative splice variant in MUC1 (a gene responsible for rare Mendelian form of kidney disease) and observe increased renal expression of a specific MUC1 mRNA isoform as a plausible molecular mechanism of the GWAS association signal." (PMID 30467309, 2018). "The MUC1 mutation is traditionally denoted as mucin 1 kidney disease or MCKD type 1." (PMID 41393609, 2025). "So far, our data suggest that HIF directly drives MUC1 expression via a regulatory DNA element just upstream of the gene in renal tubular cells and especially in tubular segments that are likely to be involved in the development of MUC1-associated kidney diseases such as ADTKD." (PMID 37316299, 2023). "By pinpointing the precise repeat unit carrying the prototypic insC we could confirm the allelic heterogeneity of MUC1 associated kidney disease." (PMID 29520014, 2018). "Thus, detection of this germline MUC1 mutation in the daughter may be considered an incidental finding in relation to kidney disease, if proven to be pathogenic in future studies." (PMID 28241424, 2017). "In humans, VNTRs have been implicated in monogenic disorders such as MUC1; however, VNTR polymorphisms also seem to influence several kidney disease related characteristics." (PMID 38707821, 2024). "Depletion of cellular mucins has hitherto only been achieved in the context of mucin 1 kidney disease, wherein a frameshifted and truncated form of MUC1 accumulates in early secretory compartments." (PMID 37537499, 2024). "Biological annotation found evidence for three novel decline-associated loci to capture common-variant-effects for genes of rare Mendelian kidney diseases (SDCCAG8, RRAGD, and MUC1), additional to the two such genes in known eGFR-decline loci (UMOD, PRKAG2)." (PMID 39567532, 2024). "We found parallel associations with eGFRcr, eGFRcys, and particularly BUN, augmenting support for a role of MUC1 in kidney disease." (PMID 37365616, 2023). "In the monogenic kidney disease ADTKD-MUC1, effects of the deleterious MUC1 variant are clearly restricted to a kidney phenotype." (PMID 37316299, 2023). "First proposed in the 2015 Kidney Disease: Improving Global Outcomes (KDIGO) consensus report, ADTKD is currently believed to be caused by gene mutations UMOD, REN, MUC1, HNF1B, SEC61A, and DNAJB11." (PMID 36362756, 2022). "In the healthy human kidney, MUC1 is expressed in distal tubule segments including the thick ascending limb (TAL) suggesting that effects on renal disease traits might be generated from this part of the nephron." (PMID 37316299, 2023). "Mutations in MUC1 are a cause of autosomal dominant tubulointerstitial kidney disease, a rare kidney disease without a cure." (PMID 31784515, 2019). "SMRT sequencing could provide a powerful tool to uncover potential factors encoded within the VNTR that associate with intra- and interfamilial phenotype variability of MUC1 related kidney disease." (PMID 29520014, 2018). "Thus, our study provides a methodological basis to sequence this region which might help to uncover the factors explaining the considerable intra- and interfamilial variability in progression of MUC1 related kidney disease." (PMID 29520014, 2018).
kidney disease (continued). "However, with our NGS panel 107, we analyzed samples of patients with inherited kidney disease from various origins and it seems very unlikely to only have samples from MUC1 patients within the same run." (PMID 38707821, 2024).
respiratory diseases (13 papers, 2015 to 2025). "MUC1, as a polymeric transmembrane glycoprotein, plays an important role in many inflammatory diseases, especially respiratory diseases." (PMID 35910848, 2022). "Up to now, MUC1/KL-6 has been studied as a diagnostic marker for respiratory disease severity, but there has been no extensive research assessing the mechanism of its overexpression." (PMID 37386665, 2022). "This study provides a comprehensive evaluation of the regulatory role of MUC1 in PM2.5-induced airway inflammation and offers new theoretical insights into potential therapeutic strategies for PM2.5-related respiratory diseases." (PMID 41181093, 2025).
bacterial infection (12 papers, 2010 to 2025). "MUC1 phosphorylation has also been linked to bacterial infection as it is induced by Pseudomonas aeruginosa." (PMID 31387973, 2019). "The gastrointestinal tract of MUC1-deficient mice was shown to be more susceptible to colonization by Helicobacter pylori, thus supporting the role of MUC1 in protecting epithelial tissues from bacterial infection." (PMID 38136848, 2023). "MUC1 expression also influences a variety of other human bacterial infections, including those by E. coli, S. enterica Typhimurium, S. pneumoniae, Staphylococcus aureus, Bacillus subtilis, Campylobacter jejuni, and Haemophilus influenzae." (PMID 35479093, 2022). "A recent study demonstrated that MUC1 facilitates phagocytosis of S. pneumoniae by macrophages and thereby limits bacterial infection." (PMID 33184103, 2020). "It has now been established that MUC1 also serves an anti-inflammatory role in the airways that is initiated late in the course of a bacterial infection and is mediated through inhibition of Toll-like receptor (TLR) signaling." (PMID 29186029, 2017). "Mucin-1 (MUC-1) forms part of the glycocalyx barrier that provides innate immune protection against bacterial infections; downregulation of MUC-1 is thought to be required for embryo attachment as the ectoderm tail presents a steric hindrance to attachment." (PMID 20707927, 2010). "In addition, enhanced inflammatory responses were observed in Muc1 knockout mice, which is in line with the anti-inflammatory effect of MUC1 during bacterial infection." (PMID 33184103, 2020). "MUC1 has also been shown to protect against bacterial infection." (PMID 31387973, 2019). "Previous studies have shown that phosphorylation of transmembrane mucin MUC1 plays a role in inflammation and bacterial infection and could be stimulated by P. aeruginosa." (PMID 31387973, 2019). "In this context, a specific question raised by our study is whether the muc1 and κ-casein in cow's milk provide optimal protection against bacterial infections of the stomach and intestine for human neonates." (PMID 21801421, 2011).
gastrointestinal tumors (9 papers, 2015 to 2025). "The preventive efficacy of MUC1-specific DNA immunization on inflammation-driven colon carcinogenesis in human MUC1 transgenic (MUC1.Tg) mice was investigated." (PMID 36980805, 2023). "We have investigated those genes (MUC1, -2, -4, -5AC, -5B, -12, -13, -15 -17, -19 and -20), which are proved to play a central role in gastrointestinal tumours, and TaqMan probe sets were available for them." (PMID 33328627, 2020). "Our previous studies using fluorophore conjugated antibodies to CEA, CA 19–9, Kit, and MUC-1 have demonstrated their capability of brightly labeling gastrointestinal tumors in vivo." (PMID 26731105, 2016).
hematological malignancies (9 papers, 2011 to 2025). "Hematopoietic cells express MUC1 to a lesser extent, but its aberrant expression has been reported in hematological malignancies." (PMID 40179083, 2025). "In the present study, we hypothesized that both genetic and epigenetic effects of the MUC1 gene may play a crucial role in the pathogenesis of cardiometabolic, renal, and hematological disorders." (PMID 34638981, 2021). "In addition, MUC1 is overexpressed and aberrantly glycosylated in hematological malignancies." (PMID 34638981, 2021). "Despite numerous molecules being validated in clinical trials, such as CEA, CD133, MUC1, GCC19 and others, the therapeutic outcomes of CAR-T cells in CRC have not been as favorable as those observed in hematologic malignancies, with the objective response rates ranging from 20% to 40%." (PMID 40721524, 2025).
inflammation (7 papers, 2015 to 2025). Aberrant reaction of the microcirculation characterized by movement of fluid and leukocytes from the blood into extravascular tissues. "Collectively, these findings confirm that MUC1 functions as a suppressor of PM2.5-induced airway inflammation by limiting epithelial injury and downregulating inflammatory signaling." (PMID 41181093, 2025). "In the present study, we established a PM2.5-induced airway inflammation model using Muc1+/+ and Muc1−/− rats, and complemented these findings with in vitro experiments using 16HBE cells transfected with MUC1 overexpression and knockdown constructs." (PMID 41181093, 2025). "Collectively, these findings demonstrate that MUC1 plays a protective role in mitigating PM2.5-induced airway inflammation and structural damage by reducing inflammatory cell infiltration, preserving epithelial integrity, and suppressing cytokine expression." (PMID 41181093, 2025). "This limits our demonstration of such findings in serum, because high serum level of anti-MUC1 antibodies can be found in patients with benign breast lesions, after breast inflammation and benign proliferative condition such as pregnancy." (PMID 26693201, 2015). "However, the specific role and molecular mechanism by which MUC1 regulates PM2.5-induced airway inflammation remain inadequately understood." (PMID 41181093, 2025). "In the present study, we demonstrated that the transcript levels for muc1, muc2, muc3, muc4, muc5b and muc13 in lung tissue were unaltered, whereas muc5ac transcript expression was significantly increased during allergen-induced airway inflammation in mice." (PMID 28205598, 2017). "Moreover, the increase in Muc1 expression induced by the Q34A peptide controls pathogenesis during airway inflammation." (PMID 27270970, 2016). "These MUC1-specific cells migrate not only to the colon but also to the pancreas of mice with IBD, which suggests that pancreatic inflammation could be the result of abnormal and proinflammatory MUC1 expression." (PMID 29075621, 2017).
benign tumors (3 papers, 2015 to 2022). "In tissue samples from patients with benign tumors, the intensity of MUC1 VU4H5 staining was very weak or moderate whereas CIN85 staining displayed a moderate intensity." (PMID 25675408, 2015). "Also, there is a humoral response to MUC-1; some patients with benign tumors had anti-MUC-1 antibodies in their blood and showed a better prognosis." (PMID 35000604, 2022). "Similarly, when investigating primary ovarian tumour samples, it was observed that MUC1/Y is more frequently expressed in malignant than in benign tumours." (PMID 34452200, 2021).